YWHAZ (tyrosine 3-monooxygenase/tryptophan 5-monooxygenase activation protein zeta)
Diseases named in the same sentence as YWHAZ in open-access papers (continued):
Sharing a sentence is not in itself a finding about the gene and the disease.
cancer (103 papers, 2008 to 2026). A tumor composed of atypical neoplastic, often pleomorphic cells that invade other tissues. "YWHAZ (14-3-3ζ), a multifunctional adaptor protein regulating cell cycle, apoptosis, and signaling, has been implicated in placental pathology and cancer biology." (PMID 41614738, 2025). "One of the genes identified in our study, YWHAZ, has been shown to exacerbate disease and is associated with poor outcomes in cancer patients." (PMID 37888708, 2023). "In PDAC cells, tumor-associated macrophages invade cancer tissues after anticancer drug treatment, and the tumor-associated macrophage-secreted YWHAZ is shown to contribute to chemotherapy resistance." (PMID 32977589, 2020). "One set includes glycolysis enzymes as well as HSP90AB1 and YWHAZ (14-3-3ζ), both of which are associated with protein-folding and promote tumour formation and cancer cell proliferation." (PMID 31560702, 2019). "Since YWHAZ has been implicated in the carcinogenesis of many cancer types, the present study provides a more comprehensive investigation to address its functional roles in UCUB development." (PMID 30945298, 2019). "Consistent with the FISH results, cancers with high YWHAZ levels associated with muscle‐invasive cancer type (p < 0.001) and higher mitotic activity (HPF ≥ 10) (p = 0.019)." (PMID 30945298, 2019). "In the present study, we identified YWHAZ as a possible cancer driver that its amplification/overexpression associates with UCUB progression and poor clinical outcomes." (PMID 30945298, 2019). "The protein 14-3-3 zeta/delta is encoded by the YWHAZ gene and has oncogenic potential in a number of cancers including CCA." (PMID 30440021, 2018). "YWHAZ (14-3–3ζ) seen in network 3, overexpressed in breast, lung and many other cancers is implicated in the initiation and progression of cancer." (PMID 22937096, 2012). "Furthermore, the protein with the most edges to other DEPs was YWHAZ, a central hub protein for many signal pathways frequently up-regulated in multiple types of cancers which is associated with cell growth, apoptosis, migration and invasion." (PMID 39223141, 2024). "The relevance of the remaining hub genes identified by our analysis of dysbiosis and T. vaginalis dysregulated miRNAs (SMAD4, UBE2I, STAT3, CDC41 and YWHAZ) remains to be investigated in the clinical context of T. vaginalis, BV and associated cancer and pregnancy complications." (PMID 36985125, 2023). "Moreover, YWHAZ is closely associated with cell growth, apoptosis and survival in cancer cells." (PMID 36834640, 2023). "Consistent with transcriptomic data, RFC2, HSP90AB1, and YWHAZ were significantly elevated in cancer patients (e.g., RFC2: 18.6 ± 2.1 ng/mL in patients vs. 8.2 ± 1.4 ng/mL in controls, p < 0.001)." (PMID 41164201, 2025). "Growing evidence suggests that YWHAZ is often overexpressed across numerous cancer types and acts as an oncogene by promoting cellular processes such as proliferation, migration, and invasion through interactions with ErbB2 and p85." (PMID 41487287, 2025). "KDELR3 and YWHAZ possessed cancer‐promoting capacities, showing promise as a novel treatment target." (PMID 38303549, 2024). "A detailed transcriptomic analysis of the pseudogenes in human cancers shows several YWHAZ pseudogenes that are distinct from the ones reported in (YWHAZP1-YWHAZP10) in Ensembl." (PMID 38674334, 2024). "YWHAZ has been reported to promote tumor growth in several cancer types and involved in PI3K/Akt signaling, emphasized YWHAZ as a prognostic factor and potential therapeutic target for GC." (PMID 38341472, 2024). "For example, YWHAZ, also known as 14-3-3ζ, is frequently upregulated in various cancers and acts as an oncogene, promoting tumor progression through multiple cellular activities." (PMID 39061176, 2024).
cancer (continued). "TGF-β released during cancer progression increases the levels of β-catenin and vimentin and promotes tumorigenesis and lung tissue fibrosis by upregulating collagen and YWHAZ expression." (PMID 37888708, 2023). "YWHAZ protein is a crucial regulator of cell growth and apoptosis pathways and is closely related to several types of cancer." (PMID 36834640, 2023). "Circ_NHSL1 is enriched in exosomes from cancer cells; therefore, it is feasible that exosomal circ_NHSL1 facilitates migration, invasion, and glutaminolysis in recipient cancer cells by upregulating YWHAZ expression." (PMID 35055115, 2022). "YWHAZ is a potential oncogene that can enhance proliferation, migration, and metastasis in many cancer types; therefore, its inhibition has strong clinical importance." (PMID 35406592, 2022). "Growing evidences showed that YWHAZ expression was commonly increased in lots of cancers and YWHAZ mediated metastasis-related protein expression." (PMID 35168653, 2022). "By suppressing such miRNAs, circ_NEK9 and circ_NHSL1 elevate the expression of microtubule-associated protein 7 (MAP7) and tyrosine 3-monooxygenase/tryptophan 5-monooxygenase activation protein zeta (YWHAZ), respectively, in cancer cells." (PMID 35055115, 2022). "To prove the validity of these in silico evaluations, we validate three novel target mRNAs by demonstrating that IGF2BP1 promotes the expression of AURKA, HDLBP, and YWHAZ in cancer cells by impairing decay of the respective mRNAs." (PMID 33829040, 2021). "Several of these events involve known cancer-related oncogenes, such as YWHAZ (8q22.3), MDM2 (12q15), and CCNE1 (19q12)." (PMID 33397444, 2021). "YWHAZ was frequently shown to be upregulated in several types of cancers, and its overexpression was often correlated with unfavorable prognosis of cancer patients." (PMID 34285141, 2021). "Univariate and multivariate analysis further indicated the prognostic potential of YWHAZ for more aggressive cancer types." (PMID 35174173, 2021). "The oncogene function of YWHAZ has been well recognized in multiple types of cancers by participating in cell growth, cell cycle, apoptosis, migration, and invasion." (PMID 33718221, 2021). "In EOC, miR‐802 inhibits the expression of YWHAZ, thereby inhibiting the proliferation, metastasis, and invasion of cancer cells, and promoting cancer cell apoptosis." (PMID 34558723, 2021). "The results showed that G3BP1 and YWHAZ were co-localised in the cytoplasm of the examined cancer cells." (PMID 32989225, 2021). "Tyrosine 3 monooxygenase/tryptophan 5-monooxygenase activation protein zeta, also named YWHAZ or 14-3-3ζ, is a key modulator of the β-catenin signaling pathway and is closely associated with tumorigenesis and cancer metastasis." (PMID 33994849, 2021). "Accumulating evidences have demonstrated that YWHAZ is frequently up-regulated in multiple types of cancers and acts as an oncogene in a wide range of cell activities including cell growth, cell cycle, apoptosis, migration, and invasion." (PMID 32127952, 2020). "To date, YWHAZ has been shown to be frequently up-regulated and function as an oncogene by regulating multiple signaling pathways in cancers." (PMID 32127952, 2020). "In BRCA, increased YWHAZ expression had been reported to induce anchorage-independent growth, malignant transformation of cancer cells, and resistance to apoptosis via inhibition of the mitochondrial apoptotic pathway." (PMID 32127952, 2020). "Growing evidences suggested the potential role of YWHAZ in cancer diagnosis, prognosis and chemoresistance." (PMID 32127952, 2020). "In this review, we seek to summarize the oncogenic role and molecular regulatory network of YWHAZ, with the aim of discovering potential clinical applications of YWHAZ regarding diagnosis, prognosis and treatment in malignant tumors." (PMID 32127952, 2020).
cancer (continued). "Growing researches have reported that YWHAZ is frequently up-regulated in multiple types of cancers, acting as an oncogene by promoting malignant properties of cancer cells." (PMID 32127952, 2020). "Targeting YWHAZ by siRNA, shRNA or miRNA was reported to have great help in suppressing malignant properties of cancer cells." (PMID 32127952, 2020). "The overexpression of YWHAZ has been reported in a wide range of cancers, and its aberrant expression contributes to cancer progression and drug resistance." (PMID 32977589, 2020). "In summary, YWHAZ is frequently up-regulated in various cancers, functioning as an oncogene by promoting the malignant phenotype of cancer cells, particularly through acceleration of migration and invasion." (PMID 32127952, 2020). "Univariate and multivariate analyses further indicated the prognostic potential of YWHAZ for more aggressive cancer types." (PMID 30945298, 2019). "Using our criteria for IHC scoring, cancer samples were stratified into Low (with scores of 0 to +2) and High YWHAZ expression (scores of +3 or +4) groups." (PMID 30945298, 2019). "Dual‐color FISH confirmed the existence of YWHAZ gain or amplification in UCUBs, especially advanced‐stage cancers (T2–T4) (p < 0.001) with lymph node invasion (p = 0.027) and higher mitotic activity (HPF ≥ 10) (p = 0.003)." (PMID 30945298, 2019). "Among these candidates, MHCC.16327 and AP003469.2 were strongly co-expressed with AC079949.2 and YWHAZ, respectively, and both genes were reported to be cancer-drivers." (PMID 31781161, 2019). "In the literature, several previous studies suggested that YWHAZ is one of the cell cycle checkpoints and has an important role in various types of cancer." (PMID 31240215, 2019). "The six main genes are involved in the cancer and inflammatory processes (YWHAZ, CCL2 and SMPD2) and lipid droplet formation and metabolism (CIDEC, VLDLR and FASN) and significantly increased in NASH patients compared to control or NAFL groups." (PMID 31717414, 2019). "YWHAZ amplification is also reported to be clinically significant in other cancer types, including breast 12, prostate 18, 20, lung 16, and oral 15, 17 cancers." (PMID 30945298, 2019). "The tyrosine 3-monooxygenase/tryptophan 5-monooxygenase activation protein zeta (YWHAZ) was identified in 55.9% of all patients’ combinations from all nine cancer types." (PMID 31695721, 2019). "Most of the evidence supporting a role for 14-3-3s in promoting chemoresistance and poor patient outcomes focuses on the 14-3-3ζ gene (YWHAZ), which resides within the 8q22.3 chromosomal region which is frequently duplicated in cancer." (PMID 29915393, 2018). "The potential of 14-3-3ζ (YWHAZ) as a target is underscored by the independent observation, based on cancer genomics of surgical specimens, that its DNA copy number and transcript levels tend to increase with PCa disease progression." (PMID 29977602, 2018). "Then, the median mutation loads for each cancer type and the median NEIL1, NEIL2, and NEIL3 expression values normalized to the expression value of the constitutive housekeeping gene YWHAZ (ENSG00000164924) were analyzed to identify correlations." (PMID 27042257, 2016). "We summarized the CNA and expression status of YWHAZ based on the study of Cancer Cell Line Encyclopedia." (PMID 27167196, 2016). "They include APOA1, VEGFC, YWHAZ, B2M, EIF2S1, CCR9 and many other genes that have been associated with the hallmarks of cancer." (PMID 25986937, 2015). "The identification of YWHAZ and other metastasis-related proteins presents novel mechanistic insights into the critical role of gankyrin in cancer metastasis." (PMID 22913272, 2012). "Furthermore, YWHAZ knockdown significantly suppressed cancer cell proliferation in cell and animal models." (PMID 41977253, 2026). "This includes several YWHAZ and its pseudogene transcripts identified in various cancer tissues." (PMID 38674334, 2024).
cancer (continued). "Similarly, overall survival and cancer-specific survival in stage I NSCLC is reported to be negatively correlated with YWHAZ, which is in line with our finding." (PMID 39075362, 2024). "We next selected YWHAZ for further evaluation in light of its reported roles in cancer." (PMID 38341472, 2024). "Moreover, inflammatory dysregulation is an intrinsic mechanism in several cancers, and YWHAZ and YWHAG are a family of phosphoserine/threonine-binding molecules that can be indirectly degraded by Serpina3n." (PMID 36673982, 2023). "The combination of YWHAZ with other cancer-specific molecules may have better capacity as a biomarker." (PMID 37525284, 2023). "YWHAZ, a member of the 14-3-3 family, affects several signaling pathways by interacting with phosphoserine- and serine-containing proteins, including β-catenin, which is involved in fibrosis and cancer." (PMID 37888708, 2023). "In addition, six genes are involved in cancer and inflammatory processes (YWHAZ, CCL2, and SMPD2) and lipid droplet formation and metabolism (CIDEC, VLDLR, and FASN) and were significantly increased in NASH patients." (PMID 36612019, 2022). "Overexpression of YWHAZ activates downstream molecules, including protein kinases, apoptotic proteins, and metastasis-related molecules, and ultimately promotes the malignant potential of cancer cells." (PMID 35027933, 2022). "Silencing FSCN1 promotes apoptosis of cancer cells with PIK3CA alterations, thus enhancing radiosensitivity, and this process may be associated with the downregulation of YWHAZ." (PMID 34249689, 2021). "Other candidates, such as AP1B1, APOA1, YWHAH and YWHAZ, however, do not appear to be associated with docetaxel resistance in cancer." (PMID 34948097, 2021). "Silencing FSCN1 enhances radiosensitivity and promotes apoptosis in cancer cells with PIK3CA alterations, and this process may be associated with the downregulation of YWHAZ." (PMID 34249689, 2021). "Previous studies also showed that YWHAZ could form a complex with β-catenin to activate Wnt pathway, thus enhancing metastatic potentials in cancers." (PMID 33718136, 2021). "Although previous studies reported that SNHG12 or YWHAZ could bind to HuR in other cancer types, this study is the first report that SNHG12 regulates the stability of YWHAZ by binding to HuR." (PMID 34195070, 2021). "Combinations of YWHAZ with other cancer-specific molecules may have better ability to serve as biomarkers." (PMID 32127952, 2020). "Given the oncogene role of YWHAZ in multiple cancers, the combination of traditional therapeutic methods and YWHAZ-targeted therapies may be an attractive project in the future." (PMID 32127952, 2020). "YWHAZ overexpression is regulated by miRNAs or long non-coding RNAs and activates downstream molecules, including protein kinases, apoptosis proteins, and metastasis-related molecules, to facilitate the malignant potential of cancer cells." (PMID 32127952, 2020). "Results from these approaches support a role for YWHAZ in promoting cancer metastasis." (PMID 32127952, 2020). "In this review, we perform literature and bioinformatics analysis to reveal the oncogenic role and molecular mechanism of YWHAZ in cancer, and discuss the potential clinical applications of YWHAZ concerning diagnosis, prognosis, and therapy in malignant tumors." (PMID 32127952, 2020). "In addition to apoptosis regulation and TGF‐β signaling, we also revealed the potential involvement of YWHAZ in regulating critical cancer phenotypes, including cancer metabolism, innate immune responses, and T cell activation." (PMID 30945298, 2019). "In addition to some RNA‐processing genes, YWHAZ was revealed to be the most cancer‐related gene in the 8q22.3 amplicon." (PMID 30945298, 2019). "Notably, cancers with high YWHAZ levels showed a higher tendency to invade the lymphatic and vascular systems (p = 0.002 and p = 0.010, respectively)." (PMID 30945298, 2019).
cancer (continued). "Given that the YWHAZ gene is situated within the 8q22 chromosomal region, which is frequently amplified in cancer, it is possible that the resulting increase in YWHAZ expression alone may position 14-3-3ζ as a dominant 14-3-3 isoform in cancer." (PMID 29915393, 2018). "Seven out of 52 genes (GSTP1, HSP90B1, HSPB1, PFN1, RAP1A, SFN, YWHAZ) were assigned to KEGG pathways in cancer, cell migration and cell cycle, and in signaling networks involved in proliferation, cellular motility, apoptosis, cell adhesion, angiogenesis and genetic integrity." (PMID 30157864, 2018). "YWHAZ/β-catenin complex is involved in drug resistance in cancer metastasis." (PMID 28981108, 2017). "Interestingly, we found that only NRAS and YWHAZ were elevated in cancer tissues compared to adjacent normal tissues." (PMID 27811373, 2016). "These genes include those mutated in other cancer types and bound with HCV proteins (e.g. PIK3R1 and EP300), genes interfacing with alternative partner groups (e.g. YWHAZ), and genes manifesting both differential co-expression and differential expression (e.g. ESR1)." (PMID 24564909, 2013). "In one study, stratifin (SFN), 14-3-3 zeta (YWHAZ), and hRNPKs (heterogeneous nuclear ribonucleoprotein K) have been identified where direct interaction between three biomarkers have been reported for their role in inflammation, signaling, proliferation, and cancer." (PMID 36776920, 2023). "Additionally, YWHAZ may be a potential biomarker of diagnosis, prognosis and chemoresistance in several cancers." (PMID 32127952, 2020). "This suggests YWHAZ could potentially serve as a cancer driver during UCUB development." (PMID 30945298, 2019). "Genes targeted by hsa-miR-22-3p, hsa-miR-18-3p, and hsa-miR-30c-5p, including the YWHAZ gene, are involved in apoptosis, TGF-β signaling, and cancer." (PMID 37888708, 2023). "Based on the Cancer Genome Atlas (TCGA) cancer database, we used LASSO regression analysis to identify the six prognostic-related genes with both DDR and EMT functions, including TP63, YWHAZ, BRCA1, CCND2, YWHAG, and HIPK2." (PMID 36673982, 2023). "The colorectal cancer related protein PABPC4 of the SARS-CoV-2 interactome interacts with YWHAQ, YWHAZ & TNFRSF10D that all involve Apoptosis59." (PMID 36463386, 2022). "It targets certain oncogenes, such as AEG-1/MTDH, PDK1, YWHAZ/14-3-3ζ, YAP and JAK2, in multiple types of carcinomas." (PMID 35205648, 2022). "Based on the dataset from TCGA 30, samples with YWHAZ genetic gain/amplification tended to also express higher mRNA (by RNA seq) and protein (by RPPA; reverse phase protein arrays) levels in their cancer tissues (p = 0.013)." (PMID 30945298, 2019). "Previous research certified that YWHAZ (also known as 14-3-3zeta) was overexpressed in NSCLC and promoted cancer progression." (PMID 30777071, 2019). "Of the genes differentially expressed between two group cancers, HTR2B, CHL1, the ZNF family, YWHAZ and FYN were the most significantly altered." (PMID 24597767, 2014). "The network includes genes that are cancer promoters and tumor suppressors such as FYN HSPA8, YWHAZ, LEPR and TGFBR2, IRF2, EP3000 respectively." (PMID 18811983, 2008). "Meanwhile, we also identified novel cancer drivers, such as PXDNL, YWHAZ and MMP9." (PMID 40478912, 2025). "Seven reference genes (YWHAZ, GNAS, GAPDH, OAZ1, PTMA, B2M, and ACTB) were screened out among the 95 candidate reference genes from the data set of the platelets’ transcriptome of pan-cancer and 73 commonly known reference genes." (PMID 35770000, 2022). "The expression of miR-802 in cancer tissues was significantly increased, and a negative relationship between miR-802 expression and YWHAZ levels was observed." (PMID 31640760, 2019). "YWHAZ belongs to the 14–3-3 gene family, which can bind to phosphoserine-containing proteins, and participates in the PI3K-Akt signaling pathway in certain cancers." (PMID 27029057, 2016).